GAS6 (growth arrest specific 6)
Diseases named in the same sentence as GAS6 in open-access papers (continued):
Sharing a sentence is not in itself a finding about the gene and the disease.
prostate carcinoma (continued). "On the other hand, the mRNA levels of Gas6 are unchanged between normal and prostate cancer tissue." (PMID 25344858, 2014). "Moreover, expression of both Gas6 and Axl is increased in ovarian, endometrial and prostate carcinomas, confirming expression of these potential targets in hormone-responsive tumours." (PMID 18283315, 2008). "Interestingly, Gas6 promotes prostate cancer cell dissemination to the bone marrow." (PMID 29386018, 2018). "Also, ERK mediates Gas6-induced human prostate cancer cell proliferation suggesting that the Gas6/Axl signaling pathway may be involved in the tumor evasion mechanism by suppressing the pro-apoptotic effects of numerous chemotherapeutics in many human cancers." (PMID 28423548, 2017). "Importantly, growth arrest specific 6 (GAS6), which influences prostate cancer dormancy, and is secreted by the osteoblastic niche, regulates part of the conversion of DTCs into CSCs through its receptor Mer, by activating the mTOR signaling pathway following cell-to-cell contact." (PMID 27172799, 2016). "We constructed ceRNA networks in the prostate cancer microenvironment and identified lncRNA LINC01082, miRNA hsa-miR-133a-3p, and genes TTLL12, PTGDS, GAS6, CYP27A1, PKP3, and ZG16B as the potential biomarkers to predict prognosis for prostate cancer." (PMID 35075375, 2022). "lncRNA LINC01082, miRNA hsa-miR-133a-3p, and genes TTLL12, PTGDS, GAS6, CYP27A1, PKP3, and ZG16B are the top RNAs having the potential to predict prognosis for prostate cancer." (PMID 35075375, 2022). "The most interesting 8 prognostic biomarkers for prostate cancer included lncRNA LINC01082, miRNA hsa-miR-133a-3p, and genes TTLL12, PTGDS, GAS6, CYP27A1, PKP3, and ZG16B." (PMID 35075375, 2022). "In prostate cancer, the activation of TAM receptors in disseminated prostate cancer cells by the osteoblast-derived Gas6 in the bone marrow induces G1 arrest and an increase in the CSC population in the microenvironment of bone marrow." (PMID 33562150, 2021). "In two additional studies, osteoblast expression of TGF-beta and Gas6, as well as BMP7, maintained bone metastatic prostate cancer cells in a dormant state, whereas reduction of those factors promoted prostate cancer cell growth." (PMID 33572757, 2021). "In a separate investigation examining mechanisms of dormancy in prostate cancer cells, reduction in osteoblast expression of TGF-beta and Gas6 led to a release from dormancy of PC3 and DU145 prostate cancer cells." (PMID 29867053, 2018). "Prostate cancer tissues and osteoblasts in “niches” can secrete Gas6, which binds to TAM receptors expressed by prostate cancer cells and induces prostate cancer dormancy." (PMID 29386018, 2018). "Clearly more work is needed in order to study the effects of caboznatinib on hypoxia and on the Gas6-AXL pathway, and the relationship of both to prostate cancer progression." (PMID 26762579, 2016). "Another example, also within the bone, occurs with the secretion of growth arrest-specific 6 (GAS6) by osteoblasts and tumor cells, which induces prostate cancer tumor cell dormancy." (PMID 26237067, 2013). "Bavdegalutamide, a proteolysis-targeting chimera (PROTAC) degrader of the androgen receptor (AR), shows promise in prostate cancer treatment, while TAM-IN-2, a TAM receptor inhibitor, effectively blocks Gas6-induced AXL activation and suppresses lung cancer progression." (PMID 40573405, 2025). "GAS6-mediated RON activation was first described in prostate cancer and has not yet been tested in comparison with HGFL activation in inflammation and wound healing models." (PMID 36833444, 2023). "Interactions between the Growth Arrest Specific 6 (GAS6) factor produced by osteoblasts and the Axl tyrosine kinase receptor expressed by disseminating prostate cancer cells, mediated the TGFβ2 signaling pathway and promoted dormancy of the tumor cells in the bone marrow niche." (PMID 35418981, 2022).
prostate carcinoma (continued). "Finally, survival analysis, biological function analysis, and literature researched identified 8 key biomarkers (lncRNA LINC01082, miRNA hsa-miR-133a-3p, mRNA TTLL12, PTGDS, GAS6, CYP27A1, PKP3, and ZG16B) to predict prostate cancer prognosis." (PMID 35075375, 2022). "In cases involving prostate cancer cells, the ANXA2/ANXA2R axis and the GAS6-AXL interaction, which both induce dormancy of cancer cells in the bone microenvironment, may represent rational targets for the therapy of skeletal metastasis." (PMID 34831167, 2021). "In addition, overexpression of the ligand to Axl, Gas6, increased expression of TGF-beta 2, which was found to mediate prostate cancer cell growth suppression in-vitro." (PMID 29867053, 2018). "In this study, we show that prostate cancer-specific hypermethylation of the eight genes AOX1, CCDC181 (C1orf114), GABRE, GAS6, HAPLN3, KLF8, MOB3B, and SLC18A2 can be detected by qMSP with very high sensitivity and specificity in scarce prostate needle biopsy samples taken at the time of diagnosis." (PMID 28084441, 2017). "In this study, we demonstrate that AXL is overexpressed and activated independent of Gas6 in docetaxel-resistant prostate cancer cells (PC3-DR and DU145-DR)." (PMID 28455956, 2017). "Taken together, these results indicate that AXL overexpression and activation, independent of Gas6, is closely related to docetaxel resistance in prostate cancer." (PMID 28455956, 2017). "Gas6/TAM is involved in the development of many cancers, including AML, ALL, schwannoma, glioma, thyroid carcinoma, ovarian carcinoma, lung cancer, gastric cancer, prostate cancer, renal cell carcinoma, breast cancer and melanoma." (PMID 28333143, 2017). "Collectively, the data demonstrate that AXL is clearly upregulated and the constitutive activation of AXL is independent of Gas6 in docetaxel-resistant prostate cancer cells." (PMID 28455956, 2017). "Unlike in other cancer types, Gas6/Axl signaling is unable to protect prostate cancer cell lines from serum starvation-induced apoptosis." (PMID 25344858, 2014). "In cells with prostate cancer, Axl expression in a hypoxic state not affected by the GAS6 so, it may be available for induction of an EMT-like condition that drives progression of metastatic condition." (PMID 31700829, 2019). "Moreover, when prostate cancer cells were injected into wild-type or GAS6-null skeletal tissue, significantly greater CSCs were identified near the endosteal surfaces of GAS6 expressing tissues compared to tissues lacking GAS6." (PMID 27172799, 2016). "Since GAS6 expressed by osteoblasts influences the proliferation of prostate cancer, and our microarray data suggests increased expression of Mer (one of the receptors for GAS6) in CSCs, we asked whether GAS6 influences the conversion of non-CSCs to CSCs." (PMID 27172799, 2016). "A recent study reported that DTCs from prostate cancer cell lines in the endosteal niche take on characteristics of cancer stem cells (CD133+/CD44+, increased KLF 4, Bmi-1, and Nanog mRNA levels), a process which was controlled by GAS6-mediated mTOR signalling." (PMID 27782035, 2016). "While GAS6-mediated activation of RON has not yet been reported in breast cancer, its effects on resistance to ADT in a RON-dependent manner in prostate cancer suggests at least some overlapping function of ligand-dependent activation irrespective of whether the ligand is HGFL or GAS6." (PMID 36833444, 2023).
breast carcinoma (45 papers, 2008 to 2025). "In breast cancer patients, expression of Gas6 was associated with a resistance against the treatment or less effectiveness of TKI therapy." (PMID 35760058, 2022). "In the breast cancer data set of 1,215 patients, Axl significantly correlates with many of the secreted factors identified on Luminex in addition to Axl associated genes Gas6 and Mer." (PMID 28008921, 2016). "EGFR associates with and transactivates Axl independently of Gas6 to amplify EGFR signaling in triple negative (TN) breast cancer cells." (PMID 25344858, 2014). "This study verifies for the first time the association between PRB and Gas6 in breast cancer tissue." (PMID 18283315, 2008). "The goals of this study were to identify Gas6 expression patterns in early and late stages of breast cancer and to determine whether tumor-derived Gas6 is associated with breast cancer progression." (PMID 32352034, 2020). "Similar to earlier studies associating Gas6 expression with favorable clinical outcome in breast cancer, Gas6 was shown to inhibit intestinal tumorigenesis in a mouse model of intestinal cancer, and Gas6 protein expression in human colorectal cancers positively correlated with prognosis." (PMID 32352034, 2020). "Growth arrest-specific gene 6 (GAS6), a vitamin K-dependent protein, is negatively correlated with its putative cis-antisense regulator, the lncRNA GAS6-AS, in breast cancer." (PMID 38475720, 2024). "Molecular analysis revealed that β-MEKDD 116 breast cancer cells increased the secretion of growth arrest-specific 6 (Gas6), a signaling molecule known to induce growth arrest in its target cells (e.g., fibroblasts)." (PMID 38106674, 2023). "Gas6/Axl mediates migration and invasion in many cancer types such as breast cancer, prostate cancer, and osteosarcoma." (PMID 36989239, 2023). "Using this system, we identified a group of genes, including Cfh, Gas6, Mme and Ogn, that were consistently up-regulated in dormant breast cancer cells compared to proliferative cells." (PMID 35093137, 2022). "We identified a group of genes commonly up-regulated in dormant breast cancer cells, including Cfh, Gas6, Ogn and Mme in two models of breast cancer dormancy." (PMID 35093137, 2022). "We identified a group of genes including Cfh, Gas6, Mme and Ogn that were highly expressed in dormant breast cancer cells present in the bone and lung." (PMID 35093137, 2022). "In support of this, it was observed that GAS6 is dispensable in a pre-clinical model of HER2+ breast cancer for the formation of metastases." (PMID 35158733, 2022). "Preclinically, the ability of warfarin to impair Gas6 function has been investigated in pancreatic cancer, lung cancer, melanoma, and breast cancer models." (PMID 34576116, 2021). "Analysis of the METABRIC and TCGA data sets showed the highest Gas6 mRNA levels in luminal A breast cancer and then a decline towards luminal B, Her2+, and basal-like." (PMID 32352034, 2020). "Despite the known tumor-promoting effects of macrophage Gas6 in vitro and in mouse models, little is known about the relevance and function of tumor-derived Gas6 in human breast cancer." (PMID 32352034, 2020). "In contrast, other studies revealed Gas6-independent functions of Axl including regulation of epithelial–mesenchymal–transition and breast cancer metastasis." (PMID 32352034, 2020). "Further analysis revealed a statistically significant reduction in Gas6 (RNA transcripts per million) in breast cancer (n = 1085) compared with normal (n = 291)." (PMID 32352034, 2020). "In breast cancer, studies have largely focused on Axl, and targeting Axl or Gas6-Axl has been proposed." (PMID 32352034, 2020). "Gas6 high patients with luminal A breast cancer showed significantly improved RFS over Gas6 low patients (n = 1933, p = 1.8 × 10−6), whereas all other subtypes showed only moderate improvement to no change in RFS." (PMID 32352034, 2020).
breast carcinoma (continued). "Gas6 has primarily been shown to be a macrophage-derived factor that activates Axl in mouse models of breast cancer, and Warfarin, an anticoagulant that blocks the interaction between Gas6 and Axl, has recently been proposed as a cancer prevention strategy." (PMID 32352034, 2020). "Patients in each data set were grouped by PAM50 score, a tumor profiling test of 50 known genes in breast cancer, to plot Gas6 mRNA levels across distinct molecular subtypes." (PMID 32352034, 2020). "Analyses of publicly available databases showed significantly improved overall and relapse-free survival in patients with high Gas6 mRNA, particularly in luminal A breast cancers." (PMID 32352034, 2020). "In a study of mouse 4T1 cells, which are highly metastatic breast cancer cells, leukocyte-derived GAS6 was shown to promote tumor growth in vivo." (PMID 32148495, 2020). "In this study, we assessed the expression pattern of Gas6 at different stages and subtypes of human breast cancer." (PMID 32352034, 2020). "Gas6 has been shown to be produced by macrophages in pre-malignant lesions of a mammary tumor model and in xenograft and orthotopic models of colon and pancreatic cancer." (PMID 32174917, 2020). "In a study in which plasma DNA was sequenced to analyse acquired resistance to cancer therapy, Gas6 was found to contribute to resistance to breast cancer therapy." (PMID 29386018, 2018). "Migration is induced in several types of cancer, including prostate and breast cancers, in response to Gas6." (PMID 29386018, 2018). "Although there is little available research on the mechanism of Gas6 overexpression, one breast cancer study showed that Gas6 is amplified in breast cancer." (PMID 29386018, 2018). "One study demonstrated the role of macrophage-derived Gas6 in experimental models of solid tumours, including colorectal cancer and breast cancer." (PMID 29386018, 2018). "Ectopic expression of TYRO3 in the MCF10A breast cancer cell line induced AKT phosphorylation in the presence of GAS6 and treatment with GAS6 promoted AKT phosphorylation in the MDA-MB435 melanoma cell line, which expresses TYRO3 but not MERTK or AXL." (PMID 30501104, 2018). "In breast cancer cells, Gas6/Axl signaling also leads to rac activation and invasion through the scaffold protein Elmo and the RHO-GTPase activator DOCK1." (PMID 26356564, 2015). "The use of bi-specific inhibitors was also proposed when it was discovered that Axl phosphorylates c-MET in response to Gas6 in TN breast cancer cells." (PMID 25344858, 2014). "In a cohort of breast cancer patients, GAS6 expression positively correlated with favourable prognostic variables such as lymph node negativity, smaller tumour size, and low Nottingham prognostic index score." (PMID 23878800, 2013). "For example, expression of Gas6 appears to be beneficial for breast cancer patients but indicates poor prognosis for gastric cancer." (PMID 21794149, 2011). "Quantitative real-time PCR analysis was used to determine the levels of Gas6 mRNA expression in 49 primary breast carcinomas." (PMID 18283315, 2008). "Further work examining the role of Gas6 as an anti-hormone treatment in breast cancer with the additional characteristic of it preventing thrombosis is an attractive area for future investigations." (PMID 18283315, 2008). "Hypothetically, an agent that targets Gas6 or Axl would benefit women with breast cancer by blocking a downstream effector of progesterone and potentially decreasing thrombosis, without causing increased bleeding." (PMID 18283315, 2008). "The current study was undertaken to validate expression of Gas6 in primary breast carcinomas and to evaluate the clinical relevance of this PRB-regulated gene in breast carcinogenesis." (PMID 18283315, 2008).
breast carcinoma (continued). "In breast cancer cell lines, Gas6 has been demonstrated to be upregulated greater than 23-fold by progesterone acting through the progesterone receptor B (PRB)." (PMID 18283315, 2008). "Overexpression of receptors for Gas6 belonging to the Axl/Tyro3 family had been reported in human mammary tumours, leukaemia and lung cancers." (PMID 18283315, 2008). "A pathway that is implicated in dormancy maintenance across multiple cancer types in bone is GAS6 expressed by osteoblast lineage cells and also breast cancer cells, binding to TYRO3, AXL or MER (TAM) tyrosine kinase receptors, although the type of receptor expressed varies across cancer types." (PMID 41091336, 2025). "As Axl has been shown to interact with EGFR in breast cancer cells and glioblastoma multiformes, we were interested in whether Gas6 can activate EGFR in both IgR3 and WM852 cells in which both Axl and EGFR are highly upregulated." (PMID 36989239, 2023). "Gas6/Axl axis contributes to chemoresistance and metastasis in breast cancer." (PMID 36059952, 2022). "Moreover, a group of genes, such as Cfh, Gas6, Mme, and Ogn, is highly expressed in dormant breast cancer cells in bone and correlated with recurrence-free survival in breast cancer patients." (PMID 35994202, 2022). "Despite the observed decreased in tumor-derived Gas6 in advanced breast cancers, targeting stromal Gas6 and its receptors remains a promising therapeutic approach and may be valuable when combined with immunotherapies." (PMID 32352034, 2020). "In addition, in breast cancer, it has been recently demonstrated that GAS6 levels, elevated in carcinoma in situ, decrease dramatically in the most invasive forms of cancer." (PMID 33182542, 2020). "In addition to reports of ligand-independent Axl-induced tumor progression, numerous studies suggest that targeting Gas6 or Gas6/Axl in breast cancer is beneficial." (PMID 32352034, 2020). "Further studies are required to understand the biological function of Gas6 in human breast cancer." (PMID 32352034, 2020). "The localization and pattern of Gas6 staining was consistent among all breast cancer subtypes." (PMID 32352034, 2020). "Interestingly, luminal A breast cancers, which generally have a favorable outcome, showed the largest percentage of patients with high Gas6 expression." (PMID 32352034, 2020). "However, only a few studies have investigated the role of Gas6-Axl signaling in the immune response to breast cancer, ovarian cancer and melanoma." (PMID 32174917, 2020). "However, few studies have addressed the expression of Gas6 and relation to overall survival in human breast cancers." (PMID 32352034, 2020). "Indeed, it is known that macrophages’ production of GAS6 is the promoter of the receptor activation on tumor cells and GAS6 levels are often elevated in breast cancer models." (PMID 33182542, 2020). "Overexpression of genes such as IL11RA, BST2 and GAS6 were important for pathogenesis of many cancer types such as gastric cancer, breast cancer, and ovarian cancer, but high expression of these genes may be responsible for advancement of GBM." (PMID 31137733, 2019). "In bone, Gas6 was shown to stimulate mouse osteoclast function via Tyro3, involving activation of Erk and Erk signalling mediated Tyro3 regulation of proliferation in breast cancer." (PMID 31766614, 2019). "The ligand for AXL; Gas6 also has a notable role in breast cancer progression." (PMID 31844158, 2019). "Upregulation of AXL and its major ligand GAS6, has been reported in a wide variety of cancer cell lines as well as in cancer specimens from patients with breast cancer, acute leukemia, colorectal cancer, lung cancer, melanoma, ovarian cancer, or prostate cancer, among others." (PMID 27829217, 2016). "In addition, they described amplification of CUL4A (25.7%), LAMP1 (13.5%), TFDP1 (31.1%), and GAS6 (13.5%) by DNA qRT-PCR on a set of 74 human breast carcinomas." (PMID 19995430, 2009).